CD4 (CD4 molecule)
Diseases named in the same sentence as CD4 in open-access papers (continued):
Sharing a sentence is not in itself a finding about the gene and the disease.
infection (continued). "Furthermore, we found a lower number of naïve CD4+ T cells and naïve B cells than we found the other subsets in old ChRM during infection." (PMID 28232735, 2017). "CD4+ T cells are known for their phenotypic plasticity, which might allow them to perform multiple functions during an ongoing infection." (PMID 28798348, 2017). "Thus, presently, no consensus exists about the relative contribution of different receptors upstream MyD88 necessary for sustaining a robust Th1 response and contributing to CD4+ T cell memory formation in a model of infection." (PMID 28895840, 2017). "In the present cohort, TNFα-producing CD4 cells were also associated with protection from infection in univariate analysis, but this association was not significant after controlling for exposure intensity and age." (PMID 29097996, 2017). "This study demonstrated that persistent IFN-I signaling during the chronic phase of infection may help to dampen HIV-1 viral replication although it also contributes to the depletion of CD4+ T cells." (PMID 29379496, 2017). "As infection progresses, CD4 T cell count progressively declines." (PMID 28265271, 2017). "However, when the epithelium is breached, HIV accesses the stroma where fibroblasts enhance infection of resident CD4+ T cells." (PMID 28207890, 2017). "CD4+ T cells with a cytotoxic phenotype arise after primary infection with hCMV in humans." (PMID 28392788, 2017). "We found that LGG attenuates the S. Infantis-induced expansion of CD4+ T-bet− IFNγ+ T cells, which could be attributed to the decline in the number of CD4+ IFNγ+T cells in peripheral blood observed 24 h after infection." (PMID 28770173, 2017). "Lymphocyte subset analysis revealed that CD4+ T cells decreased rapidly in the acute phase of infection (2 to 8 weeks post-infection) but showed transient recovery by 20 weeks post-infection, though overall the CD4+ T cells levels showed gradual decrease over time." (PMID 28787449, 2017). "However, we infer that the inability of memory CD4+ T cells to sustainably expand limits their protective effect late during infection." (PMID 29176787, 2017). "The evidence of CD8+ T cell exhaustion with simultaneous direct anti-viral CD4+ T cell effects in the chronic phase of infection led us to hypothesize that CD4+ T cells may have cytotoxic activity during chronic FV infection." (PMID 28798348, 2017). "Our previous finding that pathologic parasite-induced arginase is amplified by IL-4 in experimental VL suggests that IL-4-producing CD4+ T cells may contribute to impaired control of infection." (PMID 28103263, 2017). "Findings that prompted us to analyze and compare the cytokine mRNA profile of RRP patients with normal CD4+/CD8+ ratios as a reference group (=1) to those with the lowest CD4+/CD8+ ratios seeking for explanation of disturbed immunity as a reason for RRP infection recurrence." (PMID 28805308, 2017). "Transfer of HTLV-1 virus from dendritic cells to CD4+ T-cells or between CD4+ T-cells themselves through neo-infection mechanisms generates several infected CD4+ T-cell clones, each clone being defined by a unique integration site of HTLV-1 provirus within the host genome." (PMID 29267225, 2017). "Those in vivo-generated CD4 CTL can provide the same protection from infection as in vitro-generated cells provide evidence that the in vitro protocols use to induce CD4 cytotoxicity do approximate the mechanisms that lead to naturally occurring CD4 CTL clones." (PMID 28167943, 2017). "In this study, lack of MyD88 decreased the frequency of activated CD8+ T cells and increased the number of CD4+ T cells, which could also account for the attenuated liver immunopathology at late stages of infection." (PMID 29049365, 2017). "Multiple mechanisms, including direct infection and/or engulfment of infected CD4+ T cells by macrophages also may contribute to the infection of macrophages." (PMID 28752134, 2017).
infection (continued). "Moreover, infected cell subpopulations only partially downregulated the CD4 cell receptor upon infection, with the TEM subset being the subpopulation sustaining greater downregulation of the CD4 marker (~40% of all TEM-infected cells)." (PMID 28698276, 2017). "But it remains unknown how it evades detection within endosomes, and how internalized HIV‐1 is effectively transferred to CD4+ T cells during trans‐infection." (PMID 28923824, 2017). "Differential macrophage infections further highlighted that adaptation to usage of low CD4 levels can optimize infection of specific cell subsets and thus needs to be considered as an important parameter in shaping target cell tropism throughout disease progression." (PMID 28264054, 2017). "Despite healing of cutaneous lesions, parasites continue to persist at the original site of infection, in part due to IL-10-mediated mechanisms, and these persisting parasites are thought to help maintain effector memory CD4+ T cells (TEM) that protect against re-infection." (PMID 29167671, 2017). "Indeed, during the acute phase of infection involving innate immunity, CD4+ T cells are essential to clear Cryptosporidium spp." (PMID 29295550, 2017). "GPT levels in CD4+IFNγ-/- T cell recipients including those that succumbed to the infection were generally normal, whether treated with isotype antibody or anti-TNFα, while serum GPT was enhanced in control animals compared to non-infected mice." (PMID 28222146, 2017). "To ensure the phenotype was due to enhanced infection of CD4+ T cells, and not loss of bystander cells thus increasing the percentage of HIV-infected T cells, we conducted two experiments." (PMID 28207890, 2017). "CD4+ T cells isolated from the spleen during chronic progressive VL showed mixed expression of Th1 and Th2 cytokines and chemokines, and were marginally effective in controlling infection in an ex vivo T cell-macrophage co-culture system." (PMID 28103263, 2017). "Tissue-derived CD4+ T cells, naturally permissive to infection without exogenous activation, were also susceptible to eSF-mediated enhancement of HIV infection." (PMID 28207890, 2017). "Similarly, antigen-experienced CD4+ T cells can be tracked using surface expression of CD11a and CD49d (CD11a+CD49d+) following various infections." (PMID 28231312, 2017). "In addition, HIV-specific CD4+ T cell responses promote B cell differentiation leading to generation or maintenance of nAbs in natural infection." (PMID 28223987, 2017). "Furthermore, T cell l-citrulline metabolism is necessary for accumulation of CD4+ T cells at the site of infection, suggesting this metabolic pathway is involved during anti-mycobacterial T cell immunity in vivo." (PMID 29201027, 2017). "Next, these eight mice were intraperitoneally co-inoculated with equal amounts of hyper and hypo viruses (1,500 TCID50 each), and the amount of viral RNA in the plasma and the level of human CD4+ T cells in the peripheral blood (PB) were routinely analyzed for 6 weeks post-infection (wpi)." (PMID 28475648, 2017). "In our study, E. cuniculi infection in Cy-treated mice caused CD4+, CD8+ T cells and macrophage increase, which may be due to this secondary bone marrow stimulatory effect together with infection." (PMID 29091912, 2017). "HIV devastates the enteric immune system within days of infection, creates chronic inflammation, and immunological vulnerabilities to infections such as tuberculosis and bacterial pneumonias emerge even when CD4 levels are high." (PMID 28742819, 2017). "Finally, CD4+ macrophages transiently decreased in the submucosa and concentrated in the LP during the first days of infection." (PMID 28579989, 2017). "Experimental infections in mice demonstrated the importance of CD4+ and CD8+ IFN-γ producing T cells in maintaining a chronic T. gondii infection, but the exact contribution of each subset remains unknown." (PMID 28642841, 2017).
infection (continued). "Also, CD4+ SP cell numbers were comparable to uninfected controls by day 3 and were partially depleted only by day 4 of infection." (PMID 28091621, 2017). "However, after infection, effector/memory CD4+ T cells specific for gB and pp65 and effector/memory CD8+ T cells specific for IE-1 and pp65 become immunodominant." (PMID 29112951, 2017). "The CD4 T cell-deficient (CD4KO) mice that were pretreated with heat-killed DK128 were protected against H1N1 virus primary infection, displaying approximately 8% body weight loss and all CD4KO mice (100%) survived lethal infection." (PMID 29234060, 2017). "Furthermore, infection with Leishmania donovani affects heterologous memory as well as naïve CD4+ T cells." (PMID 28489886, 2017). "Th17 CD4+ T cells are important in host defence against a wide range of pathogens, for example, through recruitment of macrophages and neutrophils to the site of infection." (PMID 28800747, 2017). "IL-27 seems to be a key anti-inflammatory mediator in different inflammatory settings, including its relatively known role on the control of the liver immunopathology after T. congolense or T. cruzi infections and its suppressive effects on CD4 T cell subpopulations." (PMID 29033934, 2017). "Without the memory T cells present, there is no delay in onset of disease and the CD4+ T cell deficient mice challenged with serotypes B or D succumb to infection at a rate similar to the mice that were immunized with HKH99γ." (PMID 29163469, 2017). "The expression of genes related to basic composition of MHC-II like CD74 was up-regulated in CHv infected group which means the infection of CHv strain processes the potential to be presented to CD4+ cells and then evoke duck adaptive immune response in 24 hpi." (PMID 28903751, 2017). "It remains unclear why CD4+ but not CD8+ T cells are selectively associated with protection, although equally fewer CD4+ and CD8+ T cells expressing PD-1 were associated with PbNK65 hrfΔ infection." (PMID 28831137, 2017). "Nevertheless, there is growing interest in the field to understand the role of actin dynamics in HIV infection: a recent report (Ménager and Littman, 2016) points at the importance of DNM2 in dendritic cells mediated trans-enhancement of CD4 T cell infection by HIV in vitro." (PMID 28076788, 2017). "Thus, we investigated the correlation between the frequency of TIGIT-expressing CD3+CD4+ T lymphocytes and renal damage (characterized by proteinuria, hematuria, or >5 leukocytes/hpf excluding infection)." (PMID 28261278, 2017). "However unfortunately, CD2 levels rapidly and dramatically changed as soon as PBMC or CD4+ T cells were cultured ex vivo, precluding the analyses of a potential association between CD2 expression and infection in cell culture experiments." (PMID 28953327, 2017). "Remarkably, in non-infected chimeric mice, the frequencies and number of total BM T cells and BM CD4+ T cell derived from WT and Tnfrsf1-dKO donor cells were similar, whereas following infection differences in T cells derived from WT and Tnfrsf1-dKO donor cells became evident in the BM." (PMID 28671989, 2017). "To distinguish between HIV spread throughout the CD4 T cells and infection of the CD4 CAR+ CD8 T cells, we gated separately on the CD8 negative and the CD8 positive T cells, and then analyzed intracellular p24 (Gag) in CD4 T cells and CD8 T cells, respectively (see gating strategy in S1 Fig)." (PMID 29023549, 2017). "Additionally, it has been highlighted that the establishment of HIV latency and virus production from unintegrated genomes follows direct infection of resting CD4+ T-cells." (PMID 29196729, 2017). "We further observed that cell contact during infection increased viral fusion to CD4+ T cells." (PMID 28207890, 2017). "In addition, our experiments with Affinofile cells show that all infant isolates require more surface CD4 than their maternal counterparts to achieve comparable levels of target cell infection." (PMID 28122636, 2017).
infection (continued). "However, purified VLP/P10 protein given by a homologous prime-boost protocol induced a low proliferative response of CD4+ T lymphocytes evoked by P18 infection and a limited, though significant, control of the fungal burden in mice." (PMID 28938005, 2017). "During LCMV Cl-13 infection, CD4 T cells provide vital help for CD8 T-cell-mediated viral control." (PMID 28715493, 2017). "Comparisons of ectromelia virus and vaccinia virus (the active constituent of the smallpox vaccine) infection in mice showed that ectromelia virus induced significantly more CD4 CTL than vaccinia with different epitope-specific CD4 cells exhibiting different cytotoxic frequencies." (PMID 28167943, 2017). "Here we show that much of the dynamics of HIV can be explained by its impact on memory CD4+ T cell homeostasis and additionally can produce the higher infection levels observed in chronic HIV infection (CHI) compared to when ART is commenced at primary HIV infection (PHI)." (PMID 29049331, 2017). "CD4 CTL develops at sites of infections as well as inflammation." (PMID 28280496, 2017). "Interestingly, trans-infection from iDCs to CD4+ T cells is mediated through actin-rich dendrites and requires actin stabilization and inhibition of HIV endocytosis." (PMID 28207890, 2017). "Early partial control of infection was also reflected in measurements of blood CD4 + T cells." (PMID 28302457, 2017). "The studies reported here demonstrate that the decrease in both HA-specific CD4 T cells and antibody following a secondary heterosubtypic infection can be partially restored solely by establishing memory CD4 T cells against the novel HA protein prior to secondary infection." (PMID 28493882, 2017). "CD4 T cells harboring HIV-1/SIV represent a formidable hurdle to eradicating infection, and yet their detailed phenotype remains unknown." (PMID 28654687, 2017). "The low frequency of naïve CD4+ T cells before infection was strongly predictive of an increased disease progression, whereas the severe depletion of CD4+ T cells and the rapid proliferation of naïve lymphocytes accelerated the exhaustion of naïve lymphocytes in old ChRM." (PMID 28232735, 2017). "While the initial immune response partially controls HIV replication in PHI, it, however, does not eradicate the infection and does not prevent the consequent gradual loss of CD4 T cells and CD8 T-cell functional impairment." (PMID 28993778, 2017). "Tregs, in turn, control the activation of CD4+ T cells to minimize their infection by the virus." (PMID 28421070, 2017). "It is tempting to speculate that this might be one of the reasons for similar parasite burden in DC-depleted and control mice, since the critical role of CD4+ T cells during the blood-stage of infection is well established." (PMID 29085373, 2017). "The lack of impact of IL-4Rα signaling on lesion development, parasite control, and the differentiation of CD4+ Th1 cells at the site of infection and in the dLN firmly demonstrated that IL-4 signaling on keratinocytes was not involved in Th1 cell differentiation following L. major infection." (PMID 29067025, 2017). "The observed enhancement of R5 HIV-1 entry by CXCL14 was dependent on CXCR4, as infection of CXCR4-deficient GHOST cells that were engineered to coexpress CD4 and CCR5 by R5 HIV-1 was not affected by CXCL14." (PMID 28360196, 2017). "Importantly, immunized mice with preexisting LdWT infection showed significantly high multifunctional CD4+ T cells compared to naive challenged mice." (PMID 29312315, 2017). "A recent comparison of monkey species in which SIV infection is either pathogenic or non-pathogenic found higher GzmB expression in CD4 T cells from pathogenic rhesus macaques (pathogenic infection) compared to African green monkeys (non-pathogenic infection)." (PMID 28167943, 2017).
infection (continued). "Diminished IL-13 expression at this stage of infection correlated with diminished Muc5ac expression and a defect in worm clearance, while application of recombinant IL-13 or transfer of CD4+ T cells from infected WT mice was sufficient to restore worm clearance." (PMID 29045902, 2017). "In addition, we showed that the expression of GRAIL E3-ubiquitin ligase in CD4 T cells during the acute phase of infection was complemented by a high expression of inhibitory receptors such as PD-1 and CTLA-4." (PMID 28114324, 2017). "Through these experiments, it was determined that circulating H1-specific CD4 T cell memory could be established using peptide vaccination, and that the responses to this immunization were unaffected by previous infection with an H3N2 influenza virus." (PMID 28493882, 2017). "We then sought to determine whether the presence of preexisting memory CD4 T cells against the HA protein led to an increase in HA-specific antibody following secondary infection." (PMID 28493882, 2017). "Taken together, we believe that these results indicate that changes in co-receptor usage coupled to different affinities for CD4 may influence the outcome of infection with respect to IFITMs in a cell type dependent manner." (PMID 28957419, 2017). "Moreover, compared with the young macaques, the old ChRM had a more pronounced and a more proportional reduction of CCR5+CD4+ memory T cells relative to the pre-infection level." (PMID 28232735, 2017). "Infection of CD4+ cells leads to chronic immune activation and dysfunctional cytokine production." (PMID 28187438, 2017). "Importantly, the frequency of baseline CD4 responses correlated inversely with illness severity following infection, while the expansion of these responses 7 days post-challenge tracked with viral load and illness duration." (PMID 28167943, 2017). "It is notable that CD4 cells responding to immunization displayed a lower percentage of T-bet+ cells than CD4 cells responding to infection, suggesting differential strength of TCR stimulus and/or signals delivered by DCs might lead to poor Th1 commitment." (PMID 28817719, 2017). "CD4+ T cells express IFNγ in the infection of C57BL/6 as well as of BALB/c mice with R. typhi." (PMID 28770333, 2017). "Microarray studies reported that infection of CD4+ T cells with laboratory-adapted, CXCR4-tropic HIV-1 altered pathways associated with DNA repair, T cell activation, cell cycle control, subcellular trafficking, programmed cell death, RNA processing and nucleic acid metabolism." (PMID 28241075, 2017). "In this way, CXCL12 might inhibit CXCR4-tropic infection of memory CD4+ T cells and further inhibit the establishment of HIV latency." (PMID 29085362, 2017). "Percentages of Foxp-3+ HA-specific CD4+ T cells in the lungs were comparable among the mice with no treatment, with Oseltamivir only and with combinations of Oseltamivir and Rapamycin on day 7- post infection." (PMID 28646236, 2017). "Retroviruses are notorious for their immunosuppressive potential, and while the severe immunodeficiency syndrome associated with progressive HIV infection has to be attributed to the depletion of CD4+ T cells in advanced infection, all retroviruses also exhibit acutely immunosuppressive properties." (PMID 28449719, 2017). "Further, chronic HIV-2 infection is often characterized by stable CD4+ T cell counts, which may reflect an inability to efficiently establish high levels of infection in these cells in vivo." (PMID 29056936, 2017). "Finally, similar to eSF-mediated enhancement of NLENG1I, eSF enhanced BaLGFP and THROGFP infection of purified CD4+ T cells, and efficient enhancement was observed with T cells activated through either PHA/IL2- or anti-CD3/CD28." (PMID 28207890, 2017). "Therefore, we conclude that sustainable expansion and increased numbers of memory-derived CD4+ T cells late during infection would have the potential to prolong bacterial control." (PMID 29176787, 2017).